BLM (BLM RecQ like helicase)
Diseases named in the same sentence as BLM in open-access papers (continued):
Sharing a sentence is not in itself a finding about the gene and the disease.
Bloom syndrome (continued). "Under most circumstances, the pleiotropic genes responsible for POI cause syndromic POI, which manifests with highly variable somatic abnormalities in addition to reproductive phenotypes, such as BLM for Bloom syndrome and WRN for Werner syndrome." (PMID 36793102, 2023). "There were two secondary findings: one patient was found to be a carrier of Bloom syndrome (BLM gene), and one patient was found to be a carrier for Gilbert syndrome (UGTA1 gene)." (PMID 36820377, 2023). "The molecular basis for the early cancers and treatment‐related toxicities seen in patients with Bloom Syndrome is poorly understood beyond the function of BLM in maintaining genomic integrity through its DNA helicase activity." (PMID 37594403, 2023). "Building upon the associations of BLM/RECQ2 and WRN/RECQ3 with Bloom’s syndrome and Werner’s syndrome, investigations were initiated to uncover hereditary diseases linked to RECQ1, RECQ4, and RECQ5." (PMID 37626846, 2023). "The BLM gene, responsible for Bloom’s syndrome, was cloned in 1995 and found to share sequence similarities with the RECQ family of DNA helicases, including RECQL/RECQ1." (PMID 37626846, 2023). "Human Bloom’s syndrome (BLM, RecQ family) helicase plays central roles in HR pathway selection and quality control via unexplored molecular mechanisms." (PMID 35115525, 2022). "The gene associated with Bloom syndrome was mapped to human chromosome 15 and later identified as a DEAD/H-box helicase, BLMRecQ-like helicase (BLM)." (PMID 35626643, 2022). "There are five members of RecQ, which are RECQL (also called RECQL1), BLM (Bloom’s syndrome gene), WRN (Werner’s syndrome gene), RECQL4, and RECQL5 with unique biochemical functions." (PMID 35267530, 2022). "The biallelic germline mutations of BLM and FANCI resulted in Bloom syndrome and Fanconi anemia (FA), respectively, characterized by congenital disabilities and cancer predisposition." (PMID 35860547, 2022). "Another helicase from the RECQ family, namely BLM, is a DDR factor necessary for correct HR, whose mutations are associated with the cancer-prone Bloom’s syndrome." (PMID 36569948, 2022). "The clinical manifestations of patients with Bloom’s syndrome indicate that BLM activity is crucial for the maintenance of genetic stability at the organismal level." (PMID 36569948, 2022). "BLM and VHL genes also contained germline mutations leading to Bloom syndrome and Von Hippel-Lindau (VHL) disease, respectively." (PMID 36451132, 2022). "Injecting a line of Bloom syndrome cells with cDNA containing working copies of BLM results in normal rates of SCE." (PMID 35359366, 2022). "TFAM was upregulated fourfold in KSVS1452 (BLMKO) cells and 2.5-fold in Bloom- syndrome-patient-derived GM08505 (BLM−/−) cells, consistent with increased mitochondrial mass in these cells." (PMID 33495511, 2021). "Defects in BLM and WRN cause autosomal disorders: Bloom syndrome (BS) and Werner syndrome (WS), respectively." (PMID 33718381, 2021). "For example, WRN, BLM, and RECQ4 are closely associated with the Werner syndrome, Bloom syndrome, and Rothmund Thomson syndrome, respectively, for which there are currently no effective therapies." (PMID 33828983, 2021). "Furthermore, Bloom syndrome (BS) patients are predisposed to all types of cancer and cells derived from BS patients, that are defective in BLM protein, exhibit an elevated frequency of UFBs." (PMID 34530686, 2021). "Alternatively, D loops that capture the other DNA end can mature into double Holliday junctions, which can be dissolved by BLM, a RECQ helicase deficient in individuals with Bloom syndrome, or resolved by structure-specific nucleases to form crossovers." (PMID 34253720, 2021). "Genetic mutations in the BLM gene cause a rare, autosomal recessive disorder, Bloom syndrome (BS)." (PMID 33777104, 2021).
Bloom syndrome (continued). "The canonical examples are Werner Syndrome (WS) and Bloom Syndrome (BS), rare autosomal recessive disorders caused by loss-of-functions mutations in WRN and BLM respectively." (PMID 32367056, 2020). "Homozygous mutations affecting the RECQ helicases, BLM and WRN, as seen in Bloom Syndrome and Werner Syndrome, respectively, cause defective DNA repair, tumor susceptibility and abnormal development." (PMID 32369918, 2020). "Mutations in the RecQ family genes BLM and WRN are linked to rare disorders associated with genome instability, premature ageing and cancer predisposition named Bloom’s syndrome and Werner’s syndrome, respectively." (PMID 33095241, 2020). "The BLM inhibitor ML216 was the result of several iterations of chemical optimization and displays low μM activity towards BLM, and has activities on cells that induce sister chromatid exchanges, similar to the phenotype of Blooms syndrome cells." (PMID 33095241, 2020). "BLM is one of the genes responsible for Bloom syndrome and belongs to the RecQ family of DNA helicases." (PMID 32762026, 2020). "Regardless of their origins, UFBs are recognised by a UFB-binding complex comprising of PICH (Plk1-interacting checkpoint helicase) translocase, BLM (Bloom’s syndrome) helicase and its interacting factors, including TOP3A and TOP210,11,17–19." (PMID 31253795, 2019). "BLM has been confirmed in suppressing R-loop in Bloom's syndrome fibroblasts or by depletion of BLM in human cancer cells." (PMID 32010626, 2019). "To validate the immunofluorescence staining results, we examined Bloom’s syndrome fibroblast cells stably expressing a GFP-tagged BLM, and RPE1 cells expressing a GFP-tagged PLK1." (PMID 31253795, 2019). "The importance of such mechanisms is underscored by the diseases associated with deficiencies in DNA caretaker genes like CSA and CSB (Cockayne syndrome), BLM (Bloom syndrome), WRN (Werner syndrome), and ATM (ataxia-telangiectasia)." (PMID 30556094, 2019). "LOHs were generated by the combination of allele-specific double-stranded DNA breaks introduced by CRISPR/Cas9 and suppression of Bloom syndrome (BLM) gene expression by the Tet-Off system." (PMID 31805151, 2019). "Bloom syndrome (BS) is now known to be an autosomal recessive genetic disorder affecting the BLM gene, which codes for a DNA helicase protein in the RECQ family." (PMID 29610394, 2018). "In an autosomal recessive setting, each of these genes confers very rare and complex syndromes, namely Werner syndrome (WRN), Bloom syndrome (BLM), and Rothmund-Thomson syndrome or RAPADILINO syndrome (RECQL4)." (PMID 30086788, 2018). "Rqh1 is a RecQ family 3’-5’ DNA helicase that is orthologous to human WRN (Werner syndrome) and BLM (Bloom syndrome) DNA helicases, and S. cerevisiae Sgs1 DNA helicase." (PMID 28922417, 2017). "Cells from Bloom’s syndrome patients display genome instability due to a defective BLM and the downregulation of cytidine deaminase." (PMID 28947735, 2017). "BLM is a known tumor suppressor associated with higher CRC risk in heterozygotes, in addition to Bloom syndrome in homozygotes." (PMID 29212164, 2017). "BLM encodes a RECQL-DNA helicase and is involved in the recessive Bloom syndrome, which predisposes to CRC." (PMID 26901136, 2016). "Bloom syndrome (MIM 210900 for BLM) is a rare chromosome breakage disorder characterized by short stature and an extraordinary predisposition to a broad range of cancers, often multiple, early in life." (PMID 26788541, 2016). "Mutations in three of them [WRN (Werner syndrome, RecQ helicase-like), BLM (Bloom syndrome, RecQ helicase-like) and RECQ4 (RecQ helicase-like 4)] are associated with WS, BS and RTS premature-ageing syndromes, respectively." (PMID 27482812, 2016). "Relevant to this study, patients with Bloom syndrome show significantly elevated levels of UFBs as a result of defective BLM." (PMID 27977684, 2016).
Bloom syndrome (continued). "Yeast Top2 binds the Sgs1 helicase and mammalian Top2α interacts with BLM, the Bloom Syndrome helicase, and RNA helicase A, orthologous to MLE." (PMID 26053165, 2015). "BLM encodes a 3′-5′ DNA helicase which functions in maintenance of genomic stability, with inactivating mutations associated with a progeria, Bloom Syndrome (BS)." (PMID 26485759, 2015). "Comparison of E. coli RecQ and human Bloom's syndrome (BLM) ATPase cycles reveals marked differences between DNA activation mechanisms of RecQ homologs that probably contribute to their functional diversity." (PMID 25539922, 2015). "Comparison with human Bloom's syndrome (BLM) helicase reveals that similar macroscopic parameters are achieved by markedly different underlying mechanisms of RecQ homologs, suggesting diversity in enzymatic tuning." (PMID 25539922, 2015). "Bloom syndrome (BS; Online Mendelian Inheritance in Man database, number 210900) is a rare, autosomal recessive, chromosomal instability disorder caused by mutations in the BLM gene, which encodes a product necessary for the maintenance of genomic stability." (PMID 24377487, 2013). "Human RecQ homologs include RECQ1, BLM, WRN, RECQ4, and RECQ5β, three of which have been linked to diseases with elevated risk of cancer and growth defects (Bloom Syndrome and Rothmund-Thomson Syndrome) or premature aging (Werner Syndrome)." (PMID 23650516, 2013). "Missense mutations affecting the Cys residues of the Zn-binding pocket of BLM are found in Bloom syndrome patients." (PMID 24688722, 2013). "Functionally, inherited homozygous defects in BLM, WRN or RECQL4 cause human disease: Bloom syndrome, Werner syndrome and Rothmund-Thomson/RAPADILINO/Baller-Gerold syndromes respectively." (PMID 23110454, 2012). "Sgs1 is related to human RecQ helicases WRN, defective in the premature aging disorder Werner's syndrome, and BLM, defective in the cancer-prone disorder Blooms' syndrome." (PMID 22319457, 2012). "The three ORFs share the greatest homology with the BLM (Bloom syndrome) gene from humans, which is believed to act by suppressing inappropriate recombination." (PMID 23190735, 2012). "The prior probabilities were considered relatively high (0.1) due to the impact of mutations in BLM for cancer risk in Bloom syndrome patients and the functional relevance of the TOP3A for the BLM complex." (PMID 19432957, 2009). "Bloom syndrome arises through mutations in both copies of BLM gene which is located on chromosome 15 at 15q 26.1 frameshift or nonsense mutations which lead to premature termination codon and missense mutations have been found in BLM gene from BS patients." (PMID 20442845, 2009). "SGS1 is the yeast homolog of BLM, responsible for the cancer-prone Bloom's syndrome in humans, whose signature is cells with unregulated crossing-over." (PMID 19399174, 2009). "Three of the five human RecQ genes, designated BLM, WRN and RECQ4, have been genetically linked to the autosomal recessive diseases Bloom Syndrome (BS), Werner Syndrome (WS) and Rothmund-Thomson Syndrome (RTS), respectively." (PMID 18074021, 2007). "The premature aging and cancer-prone Werner and Bloom syndromes are caused by defects in the RecQ helicase enzymes WRN and BLM, respectively." (PMID 16412221, 2006).
Bloom syndrome (continued). "Mutations in HR genes can cause genome instability and predisposition to cancer; for example, ataxia telangiectasia, Nijmegen breakage syndrome, and Bloom syndrome are caused by mutations in ATM, NBN, and BLM, respectively, and are associated with pleiotropic cancer susceptibility." (PMID 39870965, 2025). "Indeed, two members of the RecQ helicase family, BLM and WRN (the proteins mutated in Bloom’s syndrome and Werner’s syndrome), are shown to play important roles in telomere elongation during ALT processes." (PMID 40025590, 2025). "Loss‐of‐function variants in BLM, a binding partner of nuclear TOP3A, cause Bloom syndrome, a rare recessive disorder characterised by short stature, predisposition to cancer and a photosensitive (butterfly) rash, associated with an elevated rate of sister chromatid exchanges." (PMID 37013609, 2023). "To address the role of sumoylation in regulation of BLM function, we introduced lysine-to-arginine mutations at amino acids 317 and 331 in a GFP-BLM expression construct and tested for complementation of cellular phenotypes of Bloom syndrome cells." (PMID 35847987, 2022). "Additionally, several of the missense mutations spreading across the helicase domain and RQC domain have also been identified and reported in the Bloom Syndrome Registry and BLM database." (PMID 33777104, 2021). "In the current cohort, BLM c.319dupT p.S106fs was detected in 2 cases: this mutation has not been described previously for Japanese persons with Bloom syndrome." (PMID 32566746, 2020). "Inactivation of RecQL2 (WRN), RecQL3 (BLM), and RecQL4 leads to Werner’s syndrome, Bloom syndrome and Rothmund–Thomson syndrome, respectively; these disorders are characterized by genome instability, increased cancer risk and, in the case of Werner syndrome, adult-onset premature aging." (PMID 32085395, 2020). "Furthermore, him-6 mutants, defective for the C. elegans orthologue of the BLM (Bloom syndrome) helicase, and smc-6 mutants, defective for the Smc5/6 cohesin-like complex, showed an increased incidence of SVs." (PMID 32358516, 2020). "There are six Japanese patients in the Bloom Syndrome Registry33,34, five of whom are homozygous/transheterozygous for the BLM c.557_559delCAA p.S186* variant, a variant not found among our cohort." (PMID 32566746, 2020). "The BLM founder mutation p.Gln548Ter, which in a homozygous state is a cause of Bloom syndrome, does not appear to predispose to breast cancer in a heterozygous state." (PMID 31614901, 2019). "These include mammalian RTEL (regulator of telomere length) and BLM (Bloom’s syndrome) helicases, which may resolve G-quadruplex structures during DNA replication." (PMID 28272375, 2017). "We first tested Bloom syndrome cells complemented with wildtype BLM." (PMID 26788541, 2016). "The BLM Bloom syndrome gene was first identified over 20 years ago." (PMID 27977684, 2016). "Finally, given that cells expressing mutant BLM that cannot bind TopBP1 display increased SCEs and chromosomal aberrations, our data may have important implications for understanding the increased cancer susceptibility and pathologies observed in Bloom syndrome patients." (PMID 25794620, 2015). "However, several DNA damage response proteins are implicated in ALT due to their association with telomeres or APBs, including the recQ-like helicases BLM (defective in Bloom's syndrome) and WRN (defective in Werner's syndrome), and the tumor suppressor BRCA1." (PMID 25084169, 2014). "The role of BLM in telomere metabolism is emphasized by telomere dysfunction in cells from those with Bloom's syndrome or cells lacking BLM, including increased telomeric associations and increased frequency of anaphase bridges involving telomeres." (PMID 25084169, 2014).
Bloom syndrome (continued). "Germline mutations in the human RecQ helicase homologs WRN, BLM and RECQ4 are responsible for the rare genetic disorders of Werner Syndrome, Bloom Syndrome, and Rothmund-Thomson Syndrome, respectively, all of which are characterized by chromosomal instability and predisposition to cancer." (PMID 23650516, 2013). "To investigate the role of BLM at telomeres, we analysed the telomere mutation frequency and profile in a BLM-deficient lymphoblastoid cell line, GM03403, derived from a donor with Bloom syndrome." (PMID 22989712, 2012). "We also suspect that a similar pathway is promoted by FANCM in humans, and in this regard it is interesting to note that the FA core complex copurifies with the Bloom syndrome complex, which contains the orthologs of Rqh1 (=BLM), Top3 (=Top3α), and Rmi1 (=BLAP75)." (PMID 18851838, 2008). "Mutations on BLM and the TRR (TOP3A/RMI1/RMI2) subcomplex have been linked to Bloom syndrome (BS) or BS-like genetic disorders, predisposing individuals to cancer development." (PMID 40846865, 2025). "BS is caused by biallelic pathogenic variants in BLM, located on chromosome 15q26, which encodes for the bloom syndrome protein (BLM) with ~300 reported cases worldwide." (PMID 40925926, 2025). "This activity also indicates that BLM functions in correcting the genomic instability characteristic of Bloom syndrome (BS)cells." (PMID 40025590, 2025). "Notably, in the absence of BLM helicase, of which mutation can cause Bloom syndrome, a cancer predisposition disorder, sister chromatid exchange events are enriched at sites with G4 motifs in transcribed genes." (PMID 36630443, 2023). "Interestingly to note, BLM, another member of the RecQ helicase family implicated in Bloom syndrome, also failed to stimulate SHOX promoter activity." (PMID 36587229, 2022). "Mutations in WRN, BLM, and RECQL4 cause Werner syndrome (WS), Bloom syndrome (BS), and Rothmund–Thomson syndrome (RTS), respectively, which are associated with premature aging, cancer predisposition, and chromosome abnormalities." (PMID 35681785, 2022). "The mutation or loss of three genes BLM, WRN or RecQ4 leads to related diseases, which are Bloom syndrome (BS), Werner syndrome (WS) or Rothmund-Thomson syndrome (RTS), respectively." (PMID 34606619, 2021). "Bloom syndrome is caused by a lack of the Bloom syndrome protein (BLM) helicase." (PMID 34885784, 2021). "In contrast, future studies in animal models in which the RPA-binding motifs in BLM and RMI1 are mutated may be informative in elucidating which function(s) of BLM are required to prevent the various pathologies with Bloom syndrome, with possible future therapeutic consequences for patients." (PMID 33500419, 2021). "Mutations in BLM, WRN, and RecQ4 cause Bloom syndrome (BS), Werner syndrome, and Rothmund-Thomson syndrome, respectively." (PMID 27601585, 2016). "WRN is a member of the RecQ helicase gene family, and other members of the family include BLM and RTS/RECQL4, which are mutated in Bloom syndrome (BS) and Rothmund–Thomson syndrome (RTS), respectively." (PMID 25688260, 2015). "Mutations in the human RecQ helicases BLM and RECQ4 also give rise to the cancer predisposition disorders Bloom syndrome (BS) and Rothmund-Thomson syndrome (RTS), respectively." (PMID 19283071, 2009). "Lack of functional BLM protein has been associated with a rare genetic disorder called Bloom syndrome (BS)." (PMID 38421735, 2024). "The BLM RecQ-like helicase prevents SCE events, therefore their identification in metaphases is a cytogenetic marker of Bloom syndrome and other syndromes of the chromosomal instability." (PMID 37052241, 2023). "Indeed, both Bloom Syndrome (BS) and BLM-depleted cells were found to be insensitive to hydroxyurea (HU) -induced replication stress, unless prolonged HU treatment is performed." (PMID 35440629, 2022). "Here, we demonstrate that the Bloom syndrome complex contains three RPA-binding motifs, two in BLM and one in RMI1." (PMID 33500419, 2021).